IL10 (interleukin 10)
Diseases named in the same sentence as IL10 in open-access papers (continued):
Sharing a sentence is not in itself a finding about the gene and the disease.
infection (continued). "At this location, regulatory immune mediators such as IL-10, TGF-β and FoxP3 were downregulated at late stages by the primary infection with F. hepatica." (PMID 36627694, 2023). "Previous MDV studies revealed that challenging chickens with MDV upregulates IL-10 expression in the spleen, including in splenic CD4+ T cells, CD8+ T cells, and γδ T cells at the later phase of infection." (PMID 36851499, 2023). "In sum, the reduced secretion of IL-10 in HLA-A11/DR1 mice leads to persistent inflammatory damage and tissue injury in the late stage of infection, promoting bacterial proliferation in both tissue and blood." (PMID 38035330, 2023). "A distinct intestinal cytokine profile was found in mice treated with canine LAB, which was characterized by higher levels of IFN-γ and IL-10, and lower concentrations of TNF-α, KC and MCP-1 than controls, in both infection models." (PMID 38076565, 2023). "The HLA-A11/DR1 mice strain induced lower levels of several cytokines (IL-2, IL-10, IL-18, IL-1β, TNF-α, IL-1α, IL-28, and ENA78), but showed increased secretion of IFN-γ, RANTES, IP10, and Eotaxin at 12 h post-infection, compared to the WT group." (PMID 38035330, 2023). "Tregs can control immune cell recruitment and proliferation and prevent exaggerated immune responses during infections by secreting TGF-β and IL-10." (PMID 37896776, 2023). "Mothers with ongoing infection exhibited higher levels of the antiviral mediator IFN-α2, the inflammatory cytokines IL-33 and TNF-α, the antiinflammatory cytokine IL-10, and the chemokine MCP-1." (PMID 37490342, 2023). "In the second phase of the infection, once parasite clearance has been achieved, anti-inflammatory mediators, such as transforming growth factor beta (TGF-β) and IL-10 are released to reduce ongoing inflammation." (PMID 37060041, 2023). "Parallelly, in the infection of Plasmodium chabaudi, TLR7 is the primary Myd88-dependent sensor at 24 hours post infection, promoting IFN-α and IFN-β production and a cytokine response (IL-10, TNF, IL-12, and IFN-γ)." (PMID 37180169, 2023). "A significantly (p ≤ 0.05) higher concentration of IL-10 was observed in Treg cell-depleted, B. burgdorferi-infected BALB/c DEREG mice than in wild-type mice treated with DTx prior to infection." (PMID 36839461, 2023). "In other experimental infections carried out in domestic pigs with highly virulent isolates belonging to genotype II (SY18, HLJ/18), increased IL-10 serum levels were also observed." (PMID 36680273, 2023). "Later during an infection, an M1 to M2 phenotypic switch can be observed, where M2 macrophages produce type III IFNs in a PPAR-γ-dependent manner and secrete IL-10 to control the immune-cell-mediated inflammatory response and mediate tissue repair." (PMID 37896776, 2023). "In young animals, TNF-α peaked at higher levels and started to decrease when IL-10 peak expression was achieved on the ninth day of infection; alternatively, in adults, TNF-α expression started to decrease before IL-10 peaked." (PMID 36839438, 2023). "While infection with NDV promotes maturation of DCs, it can also promote a more immunosuppressive phenotype measured by increased secretion of IL-10." (PMID 37974615, 2023). "High concentrations of IFNɣ, TNFα, IL-10, IL-13, and MIP-1β were found during infection, as well as high concentrations of IL-7 and MCP-1 after recovery, in both the hospital ward and the ICU." (PMID 36975498, 2023). "Vaccine dosages are commonly reported to stimulate the release of a variety of cytokines, including IFN-gamma, IL-23 (interleukin-23), IL-10, and IFN-beta, that eventually promote an immune response against infection." (PMID 37781384, 2023). "The functional QFM assay demonstrates that patients with a more robust immune response had reduced incident infection and improved survival, identifying IFN‐γ, IL‐10, and IL‐23 as possible biomarkers of outcome." (PMID 37125245, 2023).
infection (continued). "Whereas anti-inflammatory cytokines such as IL-10 and TGF-β are essential for limiting host immune response to pathogens and therefore, is known to get activated at the end after the resolution of infection to restore the normal tissue homeostasis." (PMID 37208771, 2023). "We showed that BMDCs from an early stage of AE infection expressed high levels of IL-6 and TGF-β, while IL-10 and TNF-α gene expression levels were persistently low in concordance with previous reports." (PMID 37888588, 2023). "The clinical improvements and radiological findings were also consistent with decreased levels of cytokines, such as IL-6, IL-10, TNF-α, and IFN-γ, along with improvement of inflammation and infection markers." (PMID 37041589, 2023). "Immunoglobulin (IgG) and cytokine (IL-1β, IL-6, IL-10, IFN-γ) levels were determined in ewes’ plasma collected before infection and at parturition, in lambs’ plasma at 24 and 72 h after their birth, and in colostrum samples at parturition and 72 h later." (PMID 37508158, 2023). "As depicted in, TNF-α, IL-6, IL-8, IL-10, IL-13, and IL-33 in children with HRSV were significantly increased in severe infection compared to mild infection (p < 0.05)." (PMID 37239461, 2023). "Furthermore, the slightly higher production of IL-10 in response to ZIKVPE243 in the early stages of infection (12 and 24 hpi) may be more harmful than beneficial to the pregnancy outcomes, as it could promote viral persistence and dampen host defense mechanisms." (PMID 37376550, 2023). "The levels of IL-12p70, MCP-1, IL-10, IL-1β, IFN-γ, IL-2, M-CSF, VEGF, ICAM-1, and P-selectin increased after infection; however, the expression of all except MCP-1, IFN-γ, and P-selectin was strongly suppressed by anti-TNF-α Ab treatment." (PMID 37939119, 2023). "It was also reported that the oral treatment of mice with B. longum 51A significantly increased the levels of BAL IL-10 during K. pneumoniae ATCC 27,736 infection." (PMID 37317122, 2023). "We thus compared the expression levels of proinflammatory cytokines Tnf, Il6, Il1b, and the anti-inflammatory cytokine Il10, in the lung tissues between the DMI-treated and vehicle-treated control mice during infection." (PMID 36882813, 2023). "BCG infection significantly stimulated both splenic cDC and pDC to produce IL-6, IL-10, IL-12p70, MCP-1, and TNF-α, especially at 4 h and 12 h post-infection, whereas naive DCs secreted negligible amounts of these cytokines." (PMID 36977141, 2023). "The levels of mRNA expression of pro-inflammatory (IL-6 and IL-8) and anti-inflammatory (IL-10) cytokines, as well as of type I IFN (IFN-α/β) and type II IFN (IFN-γ), were measured at 24 h post-infection in single-infected and co-infected cells." (PMID 37243291, 2023). "Elevated expression of multiple inflammatory genes, including IL6, TNF, IL10, and IL1B, were observed in the CD163+MRC1+TREM2 Mac and CD163+MRC1− subsets in both Cohort 1 and 2 after infection." (PMID 37024448, 2023). "There was a significant increase in in the secretion of cytokines IL-2, IL-6, IL-10, TNF-α, and IFN-γ in the H3N2 virus-infected group 24 hours after infection." (PMID 37900310, 2023). "Our findings further underscore that patients with severe infections, characterized by heightened levels of PCT and CRP, manifest escalated serum concentrations of IL-10." (PMID 37986183, 2023). "CD14+ monocyte-derived macrophages have an even more robust response to NDV infection, secreting high amounts of IFN, IL-6, IL-10 and TNF-α and producing toxic nitric oxide species even at low multiplicity of infection (MOI)." (PMID 37974615, 2023). "Our study revealed top 8 cytokines (IL-17, IL-1α, IL-2, IL-10, IL-5, IFN-γ, TNF-α and IL-6) and their biomarker abilities to discriminate different stages of infection." (PMID 36646786, 2023).
infection (continued). "The dual infection of PCV2b and SwIV H3N2 increased the expression of IL-10 regarding to SwIV H3N2 alone, however, the transcriptional level of this cytokine was significantly reduced in these infections compared to PCV2b single-infected cells." (PMID 37243291, 2023). "TNF-α, IL-6, IL-8, IL-10, IL-13, and IL-33 in children with HRSV were significantly increased in severe infection compared to mild infection (p < 0.05) in children with HRSV." (PMID 37239461, 2023). "Ankita identified that infection of macrophages by Mtb is recognized by TREM2 and upregulates TREM2 expression through activation of the STING pathway, which, in turn, increases IL-10 and IFN-β expression." (PMID 38203570, 2023). "The blockade of IL-10 resulted in faster infection resolution, as the intensity of IFN-γ production by CD4+ T cells was observed to correlate with healing in IL-10-/- mice." (PMID 37860064, 2023). "Flow cytometry and RT-qPCR showed that the levels of effector molecules in hepatic NK cells, such as IFN-γ, Prf1, Gzmb, IL-10, and TNF-α, were higher in Tigit-/- mice than in WT mice at 4 and 6 weeks post infection." (PMID 36930687, 2023). "IL-10 expression was significantly increased in cells infected with KP compared to uninfected cells, and treatment with the STAT-6 inhibitor during infection significantly diminished IL-10 expression in KP infected cells." (PMID 37637102, 2023). "Treg cells are able to reduce immune damage by secreting IL-10, TGF-β, as well as suppressing the cytotoxic effects of adaptive CD8+ T cells during the waning phase of infection, while promoting the maturation of memory CD8+ T cells." (PMID 37928517, 2023). "However, since IL-10 is produced by a wide array of leukocytes as well as resident CNS glia, it was of interest to explore the functional importance of IL-10 during craniotomy infection and identify the key sources of the cytokine using IL-10 conditional KO mice." (PMID 37179295, 2023). "A previous report found that the IFN-γ-deficient mice that were susceptible to the N. caninum infection produced large quantities of IL-10, but resistant wild-type mice produced considerable levels of IFN-γ and IL-4 during the acute infection." (PMID 36560492, 2022). "The ex vivo infection of SFTSV in PBMCs from healthy donors demonstrated significantly high expression levels of IL-6, IL-1β, and IL-10 induced from clade IV in either PBMCs or supernatants that were tested at 24 h after inoculation." (PMID 35603493, 2022). "We next conducted a kinetic analysis of the infection with either NH/P68 or 26544/OG10 ASFV in moMφ, moM(IL-10), moM(TGF-β) using an MOI of 0.01." (PMID 35215110, 2022). "The expression of CD11b, CD4, CD14, and CD68 for M0; IL-6, HLA/DRA, and CXCL10 for M21, and IL-10, CD163, fibronectin-1 or FN1, and CCL17 was evaluated by qPCR at 2 and 24 h after infection." (PMID 35889103, 2022). "Transcripts encoding cytokines and chemokines such as IL-1β (interleukin-1β), IL-18, IL-6, IFN-γ, IL-10, CCL2 (C-C motif chemokine ligand 2), CCL4 and CCL7 were also up-regulated in the lungs during infection." (PMID 34965194, 2022). "IL-10 and TGF-β were produced by CD25+CD127low T cells during the active infection phase, especially with N peptide stimulation." (PMID 36016311, 2022). "After 48 h of infection, the levels of TNF, CXCL8, IL6, CSF2, CD180, CD14, and CCL2 levels increased and those of IL-10, INFB1, and CXCL10 decreased." (PMID 36296238, 2022). "A cascade of biomolecular events occurs in an intricate network after exposure infection of SARS-COV-2 including the production of interleukins 1β, 6, 10 (IL-1β, IL-6, IL-10, MCP-1), and tumor necrosis factor-α (TNF-α)." (PMID 34463916, 2022). "The differentially expressed cytokines such as IL6, IL10, IL11, IL15, TNFSF10, TNFRSF6B and TNFAIP6 were detected in the lung of goats after Pm infection in this study." (PMID 35739866, 2022).
infection (continued). "These evidences suggest that IL-10, IL-6, IL-8, TNF-β, and IFN-γ are all abnormally expressed in infection." (PMID 35463642, 2022). "During the whole infection time, IFN-γ played a role mainly before 90 dpi and anti-inflammatory factor IL-4, IL-5 and IL-10 were up-regulated at or after 90 dpi, indicating a response shift from Th1-orientation to Th2-orientation." (PMID 35639780, 2022). "Since IL-10 is involved in lessening the effector CD4+ T cell responses, increased pre-infection levels of this cytokine can potentially downregulate immune responses responsible for combating HIV." (PMID 35165387, 2022). "Analysis of SNPs defining primary infection resistance revealed an enrichment for immune response genes, such as Il6, and genes involved in NF-κB and TLR signaling and confirmed IL-10 as a suitable marker disease severity." (PMID 35646724, 2022). "Five of the forty markers tested were significantly increased in K1544Δcps-infected eyes 24 h after infection: IL9, IL10, IL12-p70, MIG, and MIP-1-gamma." (PMID 35456761, 2022). "Il10−/− mice that were mock-immunized with CTB developed severe disease and lost approximately 17% body weight by day 5 post-AIEC infection." (PMID 36094114, 2022). "In contrast to what was observed with intravenous infection, we observed that after 7 days of intratracheal infection, AMΦ from BALB/c mice showed higher production of NO, TNF-α, and IL-10 than AMΦ from Swiss mice." (PMID 36520787, 2022). "Consistent with RT-PCR results, compared to the control group, the concentration of CXCL-1 and IL-10 were significantly increased in brain tissue of RS218 (p < 0.01, p < 0.001) and DE205B (p < 0.01, p < 0.01) infection groups." (PMID 36143390, 2022). "In order to evaluate the influences of CRKP colonization and translocated infection on inflammatory factor expression, interleukin-1β (IL-1β), tumor necrosis factor alpha (TNF-α), IL-6, and IL-10 concentrations were analyzed." (PMID 36445086, 2022). "Echinococcus granulosus s.s. has been shown to regulate host immunity by biasing a Th1/Th2 response towards a chronic Th2 response, as the infection was found to induce a marked increase in the transcriptional levels of IFN-γ, IL-2, IL-4, IL-5, and IL-10." (PMID 36289514, 2022). "In conclusion, we have established a connection between TLR4-NE, PKR activation, and gene expression of IFNs-I, IL10, SOD-1, and OASL2 upon infection of murine macrophages by L. donovani." (PMID 35154115, 2022). "At multiplicity of infection (MOI) of 1 and 10 bacteria per PBMC, the heat-killed cells of S. salivarius F286 and S. parasanguinis F278 induced PBMCs to secrete more IL-10 relative to IL-12, and LGG cells induced the secretion of major IL-10 and little IL-12." (PMID 35273986, 2022). "With the addition of an anti-IL-10 blocking antibody, CD4 T cell control of HCMV Merlin GFP infection increased almost to the level observed with the HCMV Merlin dUL11 GFP infections." (PMID 36445084, 2022). "Thus, whether the altered IL-10 or IL-21 expression at later or chronic stages of infection influences the likelihood of memory populations to adopt the phenotype of atypical B cells or Tr1 cells, and whether this impacts functional memory, remain priority questions." (PMID 35631044, 2022). "Additionally, it is known that IL-6, CCL2 and IL-10 could be recognized as biomarkers for P. vivax acute infection phase, however, our study is unique in proposing a coefficient combining levels of four cytokines and chemokines as biomarkers for P. vivax severity." (PMID 36178979, 2022). "Meanwhile, intestinal luminal presence of IL-10, an anti-inflammatory cytokine which negatively regulates IFN-γ production, was also increased after the infection." (PMID 35949200, 2022). "After 30 days of infection, the production of H2O2 decreased in Swiss mice, as did the production of NO, TNF-α, and IL-10." (PMID 36520787, 2022).
infection (continued). "Many inflammatory cytokines including IFN-γ, IL-6, IL-10, IL-12, IL-18, TNF-α, and CXCL9 are elevated in patients with HLH, and the cytokine patterns are helpful in differentiating HLH from infections or other inflammatory entities." (PMID 35296096, 2022). "The AUC values of IL-10, IL-17, PCT, and the combination of the three tests were much higher than those of standard laboratory infection indicators." (PMID 35937269, 2022). "Two immune genes were observed in the gene expression analysis, IL-10 and CXCL9, to be lower during the repeat infection compared to baseline." (PMID 36299763, 2022). "Regarding cDC1, the frequency of cells producing IL-10 and/or TGF-β1 reduced significantly, although with a negligible percentage of cells producing TNF-α after infection." (PMID 35720410, 2022). "An exception was the small intestine, where IL-4, IL-10, and IL-17 mRNA exceeded the amount of IFN-γ mRNA in weeks 4 and 6 post-infection." (PMID 36558820, 2022). "CD4+T cells often coproduce IL-10 and IFN-γ, designated type 1 regulatory T cells (Tr1s), and promote the onset of infection by suppressing Th1 cell-mediated immunity." (PMID 35585983, 2022). "Infection with UT127 led to the expression of the M1 markers IL12RB, IL2RB, and IFNG, concomitantly expressing the M2 markers CTLA4, IL10, and PLXNB2." (PMID 35163725, 2022). "The ability of an antigen to induce both IL-10 and IFN-γ was described for the hepatitis C virus core protein as a general homeostatic mechanism favoring the persistence of infection." (PMID 36359345, 2022). "Th cells, which are CD4+ T cells, play an important role in protecting the body from infection and secrete both proinflammatory cytokines (e.g., IFN-γ, TNF-α, and IL-6) and anti-inflammatory cytokines (e.g., IL-10)." (PMID 35001010, 2022). "In addition to NK cell activating cytokines, Ebola virus glycoprotein induces a number of anti-inflammatory cytokines, including IL-10, which are also elevated during infection and which could potentially suppress the degranulation response of post-vaccination NK cells within our PBMC cultures." (PMID 35746491, 2022). "Most strikingly, however, after infection with M. tuberculosis, the rBCG::DisA-vaccinated mice had a significantly stronger IFN-γ, IL-2 and IL-10 response in the lungs and spleen than pBCG-vaccinated mice." (PMID 35632582, 2022). "Across in ovo treatment, the expressions of IL-2, IL-6, IL-10, TGF-β4, TLR-4, 1α-hydroxylase, and VDR were significantly higher at 2 wk post-infection (28 doa) in comparison to their expression levels before coccidiosis infection (14 doa)." (PMID 36230268, 2022). "Transcriptional analysis of human monocyte-derived DCs (moDCs) infected with different Mtb strains found that infection with Mtb H37Rv led to significant upregulation of EBI3 and, compared to other mycobacteria, induced the least level of IL-10 expression." (PMID 35359957, 2022). "We observed that after sixteen hours of infection monocytes produced a significant amount of IL-1β, TNF-α, IL-6 and IL-10 in response to viable fungal spores." (PMID 36311802, 2022). "Surprisingly, another group reported that deficient T-bet B6 mice, which were not able to assemble a proper Th1, had increased levels of IL-10 during all the infection that could have contributed to the augmented susceptibility of those mice compared to wild type B6." (PMID 36678397, 2022). "Unlike conventional T cells, the most important characteristic of NKT cells in infection is the rapid activation and substantial production of cytokines such as IFN-γ, IL-10, and IL-4." (PMID 35250975, 2022). "Next, we evaluated the presence of soluble polypeptides for IFNγ, IL-1β, IL-4, IL-6, IL-8, IL-10, CXCL10, and TNFα in serum of animals following infections with Att-S74-T3Bo and Vir-S74-T3Bo." (PMID 36466866, 2022).